INS (insulin)
Diseases named in the same sentence as INS in open-access papers (continued):
Sharing a sentence is not in itself a finding about the gene and the disease.
prediabetes (continued). "More than half of our population had glucose or insulin alterations: 48% of patients had insulin levels > 10 microUI/L, while 11% had HbA1c in the prediabetes range." (PMID 37761412, 2023). "This similarity underscores the potential of the canine model in providing a more accurate representation of human insulin dynamics in prediabetes and T2DM research." (PMID 38134122, 2023). "Although the efficacy of insulin therapy cannot be doubted when the nutritional status is compromised or when metabolic deterioration is evident, this evidence is less consistent in prediabetes stages." (PMID 37371849, 2023). "Collectively, insulin appears to be a central post-prandial hormone regulating vascular function following exercise training in older adults with prediabetes." (PMID 36837756, 2023). "Intriguingly, Alistipes has been found to decrease in responders and increase in nonresponders after an exercise intervention aimed to improve glucose homeostasis and insulin sensitivity in men with prediabetes." (PMID 36728974, 2023). "There is insufficient evidence supporting a potential beneficial effect of vitamin E supplementation on improving HbA1c and fasting glucose and insulin concentrations in subjects with prediabetes." (PMID 38068801, 2023). "In the pathogenesis of prediabetes and T2DM, the role of deficient or altered levels of insulin, adiponectin, and 25 hydroxy vitamin D (25[OH]D) regulate food intake, energy metabolism, glucose and lipid metabolism, and body weight." (PMID 38068801, 2023). "The model proposed by Ha and colleagues also shows that early interventions that improve insulin sensitivity can resolve prediabetes and result in lasting remission." (PMID 38026205, 2023). "Preserving skeletal muscle mass prevents the onset of prediabetes and progression to T2D, as healthy insulin-sensitive skeletal muscle is essential to regulate glucose disposal." (PMID 38201893, 2023). "HFD destroys normal pancreas structure and affects insulin sensitivity, thereby inducing prediabetes." (PMID 37288300, 2023). "The aim of this randomized controlled trial was to examine the effects of long-term almond consumption on insulin sensitivity and glucose metabolism in males and females with prediabetes." (PMID 37258943, 2023). "The group with T2DM on insulin had higher hepcidin than controls, whilst paradoxically the group with prediabetes had lower hepcidin levels than the control group." (PMID 37029208, 2023). "Previous studies have demonstrated that hypoadiponectinemia occurs prior to a decline in insulin sensitivity and can also serve as a predictor for the transition from normoglycemia to prediabetes." (PMID 37767256, 2023). "Physical exercise not only preserves insulin sensitivity in healthy persons but can restore compromised insulin sensitivity in most subjects with overweight or prediabetes." (PMID 36774413, 2023). "Even exposure to metformin and insulin can prevent telomere attrition in individuals with prediabetes." (PMID 36979709, 2023). "Italian CFRD Screening guidelines advocate for consideration of insulin therapy for pwCF with prediabetes and indeterminate glycemia if other health metrics indicate clinical instability." (PMID 37274323, 2023). "The results show statistically lower serum adiponectin and 25(OH)D levels and higher serum insulin levels in subjects with prediabetes or T2DM compared to controls." (PMID 38068801, 2023). "The risks (OR) of prediabetes, high insulin and high HOMA-IR were lower for the upper Is tertiles than for the lowest tertile." (PMID 37819420, 2023). "Our study is the first that has combined in vitro studies and population-based studies to systematically explore the role of peripheral Aβ in insulin resistance, insulin secretion, and prediabetes." (PMID 37538787, 2023). "The majority of the participants were either normoglycemic (n = 746) or had prediabetes (n = 206), and a smaller subgroup had non-insulin-treated T2D (n = 94)." (PMID 38001287, 2023).
prediabetes (continued). "Reduced ClI emerges as a key determinant of prediabetes and T2D in adolescents who have lower insulin sensitivity, hyper-responsive β-cells, and reduced ClI compared with adults with altered glucose tolerance." (PMID 37834412, 2023). "Random Forests classifiers, based on the metabolic profiles, were used to predict the prediabetes status, and correlations of the metabolites to glycemic traits (fasting glucose and insulin, HOMA2-IR and HbA1c) and hsCRP at postpartum were evaluated." (PMID 36961590, 2023). "Taken together, our integrated approach highlighted let-7i-5p as a potential regulator of whole-body insulin sensitivity and a novel marker of prediabetes in women." (PMID 37958657, 2023). "The increase in σ and β compensates for the reduction in Si by increasing plasma insulin (I) (blue), which keeps glucose under the prediabetes level (black dotted line)." (PMID 38026205, 2023). "ClI following the OGTT was negatively associated with growing age (p = 0.006), systolic blood pressure (p < 0.001), puberty (p = 0.004), HbA1c (p < 0.001), HOMA-IR (p < 0.001), both parameters of insulin secretion (p < 0.001) and prediabetes (p = 0.022)." (PMID 37834412, 2023). "In fact, in our study, subjects that reverted prediabetes had an improvement in insulin sensitivity." (PMID 37202497, 2023). "Similar results were observed previously in a crossover RCT where prediabetes patients who adhered to TRE for five weeks experienced a significant reduction in fasting insulin levels." (PMID 37836517, 2023). "Improved pancreatic β-cell function and insulin sensitivity have been shown to increase the odds of reaching normal glucose regulation from prediabetes." (PMID 37275653, 2023). "Approximately one-third of GDM patients in our institution require insulin or OAD for glycemic control and are at high risk of developing prediabetes postpartum." (PMID 37680834, 2023). "For instance, NMN supplementation increased skeletal muscle insulin signaling, insulin sensitivity, and muscle remodeling in postmenopausal women with prediabetes, how about other populations?" (PMID 37619764, 2023). "Studies were included if they were randomized controlled trials (RCT) conducted in humans and animals that were related to prediabetes and diabetes or glucose and insulin." (PMID 36187096, 2022). "The prevailing view in the physical history of T2DM is that IR precedes causing a progressive increase in insulin secretion to compensate for IR and maintain glucose tolerance (IGT-prediabetes)." (PMID 35215472, 2022). "The aim of this study was to compare the effect of finger millet muffin and wheat muffin on glycaemic response (GR), insulin response (IR), gastric emptying (GE) and satiety in healthy individuals and people with prediabetes." (PMID 35603664, 2022). "T2D is preceded by years of prediabetes, during which the elevation of blood glucose exerts deleterious effects on β-cell mitochondria and impairs insulin secretion." (PMID 35326380, 2022). "Compared to subjects with prediabetes, those who had T2D at baseline were more likely to have higher BMI, fasting glucose, insulin, free fatty acids, triglycerides, HOMA-IR, and LP-IR and lower HDL cholesterol." (PMID 35565760, 2022). "It has been shown that a course of passive interval hypoxic exposures is effective in increasing insulin sensitivity in patients with prediabetes, decreasing blood pressure, and correcting endothelial dysfunction." (PMID 35327372, 2022). "In Aim 2, we will conduct a randomized controlled trial among a sample of food-insecure PWH who have prediabetes or T2DM to compare changes in insulin sensitivity over 6 months between participants in weCare/Secure and participants receiving usual care." (PMID 36510319, 2022). "The baseline fasting insulin in the prediabetes group and normoglycemic group was 12.61 ± 2.8 μIU/mL and 7.28 ± 0.99 μIU/mL, respectively." (PMID 35267892, 2022).
prediabetes (continued). "Blood samples were drawn and used for the analysis of the FBG and fasting insulin levels and glycated albumin to define prediabetes criteria before hematology analysis." (PMID 35497944, 2022). "T2D develops gradually, whereas prediabetes can exist for years with increased levels of insulin but relatively normal levels of overnight fasting glucose." (PMID 36364728, 2022). "In a short-term exercise intervention, Malin and colleagues investigated the effect of amount-matched intensity exercise on β-cell function, adjusting for gut hormones and skeletal muscle insulin sensitivity, among individuals with prediabetes." (PMID 35834023, 2022). "In contrast to prediabetes, there was a decrease of 2-hour postprandial insulin followed by an increase of 2-hour postprandial blood glucose." (PMID 35075363, 2022). "A decrease in TyG index in addition to the increase in insulinogenic and oral disposition indices following DPP-IV inhibition in high GLP-1 of the prediabetes subjects represents an improvement in their insulin sensitivity and beta cell function respectively." (PMID 36267570, 2022). "We conducted this cross-sectional study to assess the correlation of nesfatin-1, GSH and SOD levels with β-cell insulin secretion, and to explore their influence on insulin secretion in the development of T2DM through prediabetes." (PMID 36045734, 2022). "For example, human subjects with prediabetes treated with 6-h TRF experienced greater improvement in insulin sensitivity, blood pressure, and oxidative stress than those with 12-h TRF." (PMID 35893879, 2022). "Lastly, the effect of vitamin D supplementation on glycemic control and insulin sensitivity in subjects with prediabetes was examined in a meta-analysis of 10 randomized controlled trials." (PMID 35057492, 2022). "Training along with green coffee and chlorogenic acid supplementation improved complications of prediabetes including weight gain and elevated fasting blood glucose and plasma insulin levels." (PMID 35663196, 2022). "This study was performed to investigate the effects of bitter melon extract (BME) on glucose metabolism, insulin resistance, and various metabolic parameters of participants with prediabetes." (PMID 37009042, 2022). "Among study subjects of central obesity with prediabetes (n = 298), fasting and 2-h glucose, and fasting insulin and insulin resistance were significantly higher in Chinese than in Finnish (p < 0.0001–0.016)." (PMID 35325446, 2022). "The strengths of study include the prospective design, enrolment of a diverse study cohort, and the use of robust methodologies for assessment of prediabetes endpoints, insulin sensitivity and insulin secretion." (PMID 36686435, 2022). "In a recent study, NMN supplementation increased muscle insulin sensitivity, insulin signaling, and remodeling in overweight or obese women with prediabetes." (PMID 36139711, 2022). "Specifically, among older adult participants with prediabetes and central obesity, fasting glucose, insulin, HOMA-IR, and TG were significantly higher, while LDL and LDL/HDL ratio were lower, in Chinese individuals than in Finnish individuals." (PMID 35325446, 2022). "A recent clinical study demonstrated improved insulin sensitivity in the hypothalamus in subjects with prediabetes after treatment with Empagliflozin." (PMID 35707855, 2022). "Cluster analyses have proposed different prediabetes phenotypes using glycemic parameters, body fat distribution, liver fat content, and insulin sensitivity." (PMID 36072936, 2022). "In another study, 12-week intense exercise-induced changes in the gut microbiota in subjects with prediabetes with marked improvement in insulin resistance and reduced insulin level." (PMID 35600606, 2022). "As such, it is possible that insulin, and perhaps some prediabetes HbA1c testing, was underreported." (PMID 36411411, 2022).
prediabetes (continued). "Type 2 Diabetes (T2D) results from a progressive loss of pancreatic islet function followed by long-term insulin resistance and elevated insulin secretion Prediabetes is an intermediate condition that precedes TD2." (PMID 36046788, 2022). "As persons with prediabetes are already insulin resistant, a higher postprandial glucose response after consumption of carbohydrate-rich foods compared to that of a healthy population is to be expected." (PMID 36364728, 2022). "The increasing prevalence of OSA and the increasing number of patients with T2D and prediabetes suggest that evaluating the therapeutic interaction of GABA with insulin-secretion processes under IH conditions is an urgent public health issue." (PMID 36138614, 2022). "Physical activity has benefits in increasing insulin sensitivity and glycemic control in all ranges of the population, from children to older adults, including healthy people, prediabetes, and T2DM patients." (PMID 35633269, 2022). "The patterns showed better AUC and diagnostic sensitivity for prediabetes screening of IGT than FPG, HbA1c, insulin, or a combination of FPG and HbA1c." (PMID 35909528, 2022). "It has been shown that lifestyle modification, including caloric restriction and exercise, are safe, non-invasive interventions that effectively attenuate prediabetes via an improvement of insulin sensitivity." (PMID 35272616, 2022). "The mitochondrial abnormalities observed in insulin-resistant skeletal muscle are notable since this tissue is the main site of insulin-stimulated glucose uptake and thus consequential to glucose dysregulation, as occurs in prediabetes and T2D." (PMID 36093112, 2022). "Those with prediabetes and T2D were also more likely to have a higher BMI as well as higher fasting glucose, insulin, free fatty acids, triglycerides, GlycA, HOMA-IR, and LP-IR and lower HDL-cholesterol." (PMID 35565760, 2022). "On subgroup analyses, we observed that N. sativa supplementation significantly reduced fasting insulin concentration among subjects with prediabetes." (PMID 36034891, 2022). "IR, impaired insulin function, and hypersecretion of insulin are the main factors in prediabetes pathophysiology." (PMID 34099024, 2021). "A randomized clinical trial performed to assess the effect of dietary intervention in subjects with prediabetes demonstrated improved post-intervention fasting glucose and insulin resistance." (PMID 33467197, 2021). "We observed that oral delivery of the TZD pioglitazone (PIO), an insulin-sensitizer prescribed to patients with prediabetes or existing T2D, counteracted these pathological metabolic outcomes." (PMID 34572374, 2021). "Normally, during nutrient intake, insulin secretion is increased and glucagon secretion is repressed, but when plasma glucose concentration increases, a state of prediabetes occurs." (PMID 34829598, 2021). "Insulin sensitivity was also significantly improved in the LM group, consistent with previous trials in prediabetes using incretin therapies." (PMID 33888772, 2021). "Given that most of the dysglycemic group had prediabetes, we also compared insulin homeostasis traits in those with normal glucose tolerance to those with prediabetes (IFG and/or IGT), IFG, or IGT." (PMID 34206745, 2021). "Using xylooligosaccharide lowered OGTT 2 h insulin levels in adults with prediabetes, suggesting that these prebiotics are more beneficial in alleviating the risk factors of T2D than treating it." (PMID 34684121, 2021). "Despite still being under debate, reactive hypoglycemia after ingestion of especially carbohydrate-rich food due to increased peripheral insulin resistance and disturbed insulin secretion has been suggested in prediabetes." (PMID 33952305, 2021). "In this relatively healthy prediabetes cohort, the mean baseline measures for fasting glucose, insulin, lipoproteins, TG, hs-CRP, and blood pressure were generally within the normal range." (PMID 34201139, 2021).
prediabetes (continued). "Six months after bariatric surgery, individuals with prediabetes showed an improvement in whole-body insulin sensitivity, which correlated positively with the decrease in myocardial fasting free fatty acid uptake, but also myocardial function." (PMID 34827678, 2021). "Pancreatic β-cells adapt to impaired glucose regulation in prediabetes by increasing insulin secretion and β-cell mass expansion." (PMID 33401592, 2021). "One of the strengths of our study is that β-cell dysfunction and lower insulin sensitivity provide physiological information on early abnormalities in glucose metabolism that eventually result in prediabetes and T2D." (PMID 31486878, 2020). "The objective of this study was to assess the effect of vitamin D3 supplementation on oral glucose insulin sensitivity (OGIS) index in patients with prediabetes and hypovitaminosis D." (PMID 33457118, 2020). "The purpose of this study was to investigate the effects of the regular daily intake of magnesium-rich BDSW on improving glucose and insulin-sensitivity parameters, as well as the overall lipid profile in prediabetes subjects." (PMID 32085495, 2020). "Specifically, in 157 Asian Indians residing in western India, vitamin D deficiency/insufficiency was found in 115 (73.25%) individuals with prediabetes and those with lowest 25(OH) D levels (<10 ng/ml) had the highest insulin resistance." (PMID 31937856, 2020). "For individuals with prediabetes, a diet that includes dairy decreases postprandial glucose, insulin, and triglyceride response compared with a red meat/refined carbohydrate diet." (PMID 33322540, 2020). "Pistachio also demonstrated positive correlations with glucose and insulin related parameters, urine metabolites and creatinine levels in prediabetes." (PMID 33003593, 2020). "This highlights that all treatments improved hepatic insulin sensitivity in middle-aged adults with prediabetes." (PMID 32849302, 2020). "Do the postprandial insulin-glucose axis abnormalities, HOMA-IR and adipo-IRi elevations reflect early risk for prediabetes?" (PMID 32272872, 2020). "In stepwise multiple regression analyses high VAT volumes are superior to high BMI, hip/waist circumference, and WHR in determining both low insulin sensitivity and prediabetes." (PMID 32664590, 2020). "In conclusion, our current results demonstrated the efficacy of magnesium-rich BDSW supplements in improving insulin-sensitivity parameters and lipid profiles in patients with prediabetes." (PMID 32085495, 2020). "Although Enzogenol® appears to show hypoglycaemic potential, future studies are warranted to examine the effect on other measures, such as insulin, and in other population groups, such as those with prediabetes or T2DM." (PMID 32075228, 2020). "In a cross-sectional study of 488 subjects, those having prediabetes and low circulating 25(OH)D concentration were most insulin resistant and had impaired beta cell function." (PMID 31937856, 2020). "The extent of visceral adipose tissue (VAT) correlates negatively with insulin sensitivity and positively with the incidences and development of prediabetes, T2DM, and cardiovascular diseases." (PMID 32566685, 2020). "The improvement in insulin sensitivity/glycemic control by the correction of subnormal vitamin D in prediabetes subjects has been reported by various studies." (PMID 33457118, 2020). "The correction of hypovitaminosis D in subjects with prediabetes led to improved insulin sensitivity as assessed by OGIS index at 120 minutes, signifying the role of vitamin D in glucose homeostasis." (PMID 33457118, 2020). "In summary, the NZO mouse reflects important characteristics of human GDM and prediabetes in pregnancy and serves as a model for subpopulations with early alterations in glucose metabolism and primary insulin secretion defect." (PMID 32374082, 2020).